ACSM4 (acyl-CoA synthetase medium chain family member 4)
Description:
Catalyzes the activation of fatty acids by CoA to produce an acyl-CoA, the first step in fatty acid metabolism (By similarity). Capable of activating medium-chain fatty acids with a preference for C6-12 fatty acids (By similarity).
Tractability: No criterion of Open Targets' tractability assessment is met for any kind of drug.
Gene: Protein-coding gene on chromosome 12 (7,304,072 to 7,328,719, forward strand). Ensembl gene ENSG00000215009.
Subcellular location: Mitochondrion
Pathways (Reactome):
Drug ADME: Aspirin ADME
Metabolism: Conjugation of salicylate with glycine
Gene Ontology:
Molecular function: decanoate-CoA ligase activity; fatty acid ligase activity; fatty-acyl-CoA synthase activity; medium-chain fatty acid-CoA ligase activity; CoA-ligase activity
Biological process: acyl-CoA metabolic process; fatty acid biosynthetic process
Cellular component: mitochondrion; mitochondrial matrix
Genetic constraint (gnomAD): Loss-of-function variants: 65 observed, 74.56 expected, observed/expected ratio (o/e) 0.87, 90% interval 0.71 to 1.07. The upper end of that interval is the gene's LOEUF score, 1.07, which puts it in group 4 of 6, group 1 being the genes least tolerant of losing a copy. Missense variants: 641 observed, 725.62 expected, observed/expected ratio (o/e) 0.88, 90% interval 0.83 to 0.94. Synonymous variants: 221 observed, 259.98 expected, observed/expected ratio (o/e) 0.85, 90% interval 0.76 to 0.95.
Homologues: Orthologues: chimpanzee ACSM4 (99% identical), macaque ACSM4 (96% identical), mouse Acsm4 (86% identical), rat Acsm4 (86% identical), guinea pig ACSM4 (85% identical), pig ACSM4 (84% identical), tropical clawed frog acss2.2 (27% identical), zebrafish acss2l (24% identical), Caenorhabditis elegans acs-2 (19% identical), Caenorhabditis elegans acs-1 (18% identical). Paralogues in human: ACSM5 (61% identical), ACSM3 (59% identical), ACSM2A (57% identical), ACSM2B (57% identical), ACSM1 (54% identical), ACSM6 (38% identical), ACSS2 (27% identical), ACSS1 (27% identical), ACSS3 (24% identical), AACS (22% identical), ACSF2 (22% identical), ACSF3 (21% identical), and 1 more.
Diseases named in the same sentence as ACSM4 in open-access papers:
ACSM4 is named in the same sentence as 3 diseases in open-access papers, as found by Europe PMC text mining. Sharing a sentence is not in itself a finding about the gene and the disease. The quoted sentences say what the papers report.
triple-negative breast carcinoma (1 paper, 2023). An invasive breast carcinoma which is negative for expression of estrogen receptor (ER), progesterone receptor (PR), and human epidermal growth factor receptor 2 (HER2). "ACSM4 is associated with poor prognosis of triple-negative breast cancer." (PMID 37426827, 2023).
ACSM4 also shares sentences with these, for which no sentence is quoted: AIDS (1 paper); breast carcinoma (1).